INS (insulin)
Diseases named in the same sentence as INS in open-access papers (continued):
Sharing a sentence is not in itself a finding about the gene and the disease.
osteoporosis (141 papers, 2010 to 2025). A condition of reduced bone mass, with decreased cortical thickness and a decrease in the number and size of the trabeculae of cancellous bone (but normal chemical composition), resulting in increased fracture incidence. "Studies should focus on elucidating the molecular mechanisms underlying insulin’s influence on skeletal remodeling, including its effects on osteoblast and osteoclast activity, to develop targeted therapies for osteoporosis and metabolic bone diseases." (PMID 40725728, 2025). "This is clinically significant, as LBM reduction is linked to health issues like decreased metabolic rate, reduced insulin sensitivity, and increased osteoporosis risk." (PMID 40455565, 2025). "Excessive Hsd11b1 activation elevates local glucocorticoid activity in adipose and bone tissues, thereby promoting visceral fat accumulation, impaired insulin sensitivity, and osteoporosis associated with aging." (PMID 41019552, 2025). "In this work, we examined the relationship between the risk of osteoporosis and the dietary insulin score." (PMID 39004741, 2024). "The second reason is that the case-control design of this study precludes the examination of a coincidental relationship between the risk of osteoporosis and the dietary insulin index." (PMID 39004741, 2024). "Deficiency of Mn, Cr, Cu, Fe and Zn have been associated with scaly dermatitis, increased insulin requirements, osteoporosis, anemia and impaired immunity respectively." (PMID 37416859, 2023). "New data showed promising biomarkers such as increased galanin in the hypothalamus that was found in T2DM-associated osteoporosis underlying galanin control over insulin sensitivity and bone density." (PMID 38068450, 2023). "It was found that both methods induced typical adverse outcomes such as fat accumulation, insulin resistance, muscle loss and osteoporosis." (PMID 37964970, 2023). "On the other hand, low LM values relate to metabolic risk factors and resistance to insulin, and including the risk of osteoporosis." (PMID 31555209, 2019). "Our analyses suggest that osteoporosis is related to testosterone deficiency and is independent from insulin activity." (PMID 29867095, 2018). "Only considering the over-representation evidence, we identified another two significant pathways with FDR≤0.20, Insulin signaling pathway and mTOR (mammalian target of rapamycin) signaling pathway, which has been reported to be associated with osteoporosis." (PMID 26390436, 2015). "Interventional studies comparing the effect of vitamin D supplementation on insulin action and secretion, in ME immigrants and native Europeans, are needed as well as cohort studies addressing the incidence of osteoporosis and fracture risk in relation to the levels of 25(OH)D, PTH and Calcium." (PMID 39712337, 2025). "Studies have previously reported a disruption mediated by chemerin in bone metabolism and insulin signaling in muscle, which may contribute to the muscle wasting, osteoporosis, and associated frailty in people with metabolic disorders." (PMID 40561128, 2025). "Two factorsthat impact bone formation are the accumulation of advanced glycation end productsin collagen and oxidative stress resulting from elevated blood glucose levels.Furthermore, the occurrence of osteoporosis has been associated with reduced levelsof insulin and insulin-like growth factor-1." (PMID 41259452, 2025). "Thus, we aimed to investigate the association of glycemic and insulin indices with the odds of osteoporosis in a large sample of the Iranian adult population." (PMID 39839276, 2024). "Lower glycemic and insulin indexes can reduce inflammation, which may underlie osteoporosis progression." (PMID 39839276, 2024). "Insulin injection could increase fracture risk, meanwhile, the effects of anti-osteoporosis drugs become weaker for diabetic patients." (PMID 36589835, 2022).
osteoporosis (continued). "Manganese deficiency may result in osteoporosis, impaired insulin production, alteration in lipoprotein metabolism, an impaired oxidant defence system, fatigue, and abnormalities in growth factor metabolism." (PMID 29026589, 2017). "Additionally, an in-depth exploration of the regulatory mechanisms of vitamin D receptor (VDR) gene polymorphisms in T2DM-associated osteoporosis is warranted, including the specific signaling pathways these receptor genes participate in and their correlation with insulin or glucose metabolism." (PMID 39897963, 2024). "BP therapy is beneficial in MP-associated osteoporosis and may improve fasting plasma glucose, HbA1c, and insulin indices in postmenopausal women; however, the treatment compliance is still reduced, and efficacy may be genetically influenced by non-responders to therapy." (PMID 36983805, 2023). "The authors found that the BMD was higher, but bone markers (OCN and CTX) were lower in postmenopausal women with T2DM and treated with insulin as compared to postmenopausal women with osteoporosis." (PMID 40564223, 2025). "The proteins of the AFI axis are part of the TGF-β superfamily, and the AFI axis plays an important role in regulating reproductive function, tissue development, insulin sensitivity (energy supply), muscle wasting, and osteoporosis." (PMID 40144023, 2025). "Several studies have demonstrated the existence of a positive correlation between osteoporosis and glycemic and insulin indices in specific populations." (PMID 39839276, 2024). "Compared to previous decades, in the 2010s there was a particular interest in the study of micronutrients, osteoporosis, anemia, and insulin resistance, related to surgical techniques such as sleeve gastrectomy and Y-de-Roux gastric bypass." (PMID 39001982, 2024). "In the case that a significant negative association between DII and the incidence of osteoporosis were discovered, we would conclude that eating meals with high insulin index would be essential for postmenopausal women to avoid osteoporosis." (PMID 39004741, 2024). "Odds ratio (OR) and 95% confidence interval (CI) for osteoporosis based on dietary insulin and glycemic scores among participants." (PMID 39839276, 2024). "So, it seems that the role of the dietary insulin response in osteoporosis development requires further investigation." (PMID 39839276, 2024). "GLP1R is a G-protein-coupled receptor for GLP-1, which, when activated, regulates insulin secretion and thus influences osteoporosis." (PMID 38200769, 2023). "The search string used for the literature search was “(insulin OR “insulin receptor” OR “insulin-like growth factor-1” OR IGF-1) AND (Wnt OR beta-catenin) AND (bone OR osteoporosis OR fracture OR osteoblast OR osteoclast OR osteocyte)”." (PMID 37569816, 2023). "People with paralysis are unable to contract their muscles which atrophy, transform into insulin resistant glycolytic muscle, and develop osteoporosis." (PMID 36278750, 2022). "Studies also showed that uptake of trehalose reduce insulin resistance and osteoporosis development and maintains glycogen-trehalose balance in the body." (PMID 35164374, 2022). "This is consistent with observations that COPD is associated with extrapulmonary diseases such as cardiovascular disease, osteoporosis, muscle wasting, and insulin resistance." (PMID 33987620, 2020). "Insulin studies analyzed the faster response and persistence of MNs, whereas osteoporosis and migraine studies compared and analyzed the effective indicators of drug delivery using MNs." (PMID 33228098, 2020). "For osteoporosis treatment, vaccine, and insulin delivery studies, MNs were comparable to or more effective than the gold standard." (PMID 33228098, 2020). "Although we have not been able to analyze all of these rapidly changing and latest knowledge, in this review, MNs for influenza, rabies, poliovirus vaccine, insulin delivery, osteoporosis, and migraines were discussed." (PMID 33228098, 2020).
osteoporosis (continued). "MNs have been used in the treatment of skin diseases (i.e., scar, wrinkle, alopecia, AK, wart), delivery of specific drugs (i.e., vaccine or insulin delivery), and for other medical purposes (i.e., osteoporosis, migraine, axillary hyperhidrosis)." (PMID 33228098, 2020). "In patients with osteoporosis, serum chemerin level was positively correlated with serum insulin level (R = 0.459, P < 0.01) and negatively correlated with LDL-C (R = −0.316, P < 0.01)." (PMID 26170530, 2015). "The long-term application of dexamethasone also induces osteoporosis and decreases insulin sensitivity." (PMID 26581842, 2015). "Therefore, for patients with higher TyG levels, treatment should extend beyond conventional osteoporosis management to address related metabolic conditions, such as improving insulin sensitivity and adjusting lipid metabolism." (PMID 40370776, 2025). "Current research focuses on three main areas: the association between osteocalcin levels and diabetic complications, the clinical efficacy of drugs or vitamins for osteoporosis in diabetic patients of different ages and sexes, and the potential mechanism of insulin regulation by osteocalcin." (PMID 39872315, 2024). "Therefore, close monitoring of bone mass in insulin-resistant individuals and early implementation of preventive strategies are crucial in mitigating the occurrence of low bone mass and osteoporosis." (PMID 37904197, 2023). "In addition, the combined use of glimepiride and recombinant human insulin injection prevents the occurrence of complications such as osteoporosis." (PMID 35571731, 2022). "The occurrence of T2DM combined with osteoporosis may be related to inhibition of the liver insulin signaling pathway." (PMID 35957821, 2022). "Blockade of receptor activator of nuclear factor kappa-B ligand (RANKL) improves osteoporosis, but might also improve glucose tolerance through reduction of hepatic insulin resistance." (PMID 31764838, 2019). "It has been found that IR induced by 12-week high fat diet (HFD) could impair the osteoblastic insulin signaling, osteoblast proliferation, and osteoblast survival and result in osteoporosis of the jawbone." (PMID 23983685, 2013). "The subjects in the osteoporosis group were older, and consequently had higher average post-menopausal years; however, they had significantly lower BMI, lower waist and hip circumferences, and lower fasting glucose, insulin, and triglyceride levels compared to the normal BMD group." (PMID 40011291, 2025). "Consequently, it may be essential for postmenopausal women to consume nutrients that stimulate insulin production in order to prevent osteoporosis." (PMID 39004741, 2024). "Sixth, antidiabetic therapy: Cipriani and his colleagues reviewed the published studies and found that long-term use of antidiabetic drugs such as insulin and thiazolidinediones can have a negative impact on bone health, which is one of the risk factors for fracture and osteoporosis." (PMID 39687075, 2024). "Consequently, it may be essential to consume nutrients that stimulate insulin production in order to prevent osteoporosis." (PMID 39004741, 2024). "It is, therefore, reasonable to infer that MMP2 could be a therapeutic target for the treatment of osteoporosis.SORBS1 refers to the insulin signaling molecules expressed in fat and skeletal muscle that is involved in the regulation of signaling pathways within the cytoskeleton." (PMID 38099525, 2024). "Finally, results from the Canadian Multicentre Osteoporosis Study (CaMos) showed that sclerostin levels are associated with fasting insulin levels and HOMA-IR, but not with the risk of incident T2DM." (PMID 32265831, 2020). "Arginine stimulates insulin and IGF-1 secretion, both known as protective factors against osteoporosis, through promoting osteoblast proliferation and collagen synthesis." (PMID 40385578, 2025).
osteoporosis (continued). "This study aimed to investigate the potential association between dietary glycemic index (DGI), dietary glycemic load (DGL), dietary insulin index (DII), dietary insulin load (DIL), and the odds of osteoporosis among Iranian adults." (PMID 39839276, 2024). "Drugs used in these patients such as metformin, sulfonylureas, dipeptidyl peptidase-4 inhibitors (DPP4 inhibitors), insulin, and GLP-1 receptor agonists are noted to be better in terms of osteoporosis." (PMID 37680820, 2023). "In patients with osteoporosis, inhibition of RANKL improves muscle strength and insulin sensitivity." (PMID 32265831, 2020). "Most studies indicated that in nondiabetic postmenopausal women with osteoporosis, denosumab did not exert significant effects on insulin secretion or insulin resistance." (PMID 40149867, 2025). "The participants were divided into four groups, including healthy postmenopausal women, postmenopausal women with osteoporosis, T2DM postmenopausal women treated with insulin once daily, and T2DM postmenopausal women treated with metformin (500 mg) twice daily." (PMID 40564223, 2025). "Furthermore, significant difference were observed in history of osteoporosis/brittle bones, levels of HbA1c, FPG, serum INS, HOMA-IR, sCr, UA, TBL and 25(OH)D among the three groups." (PMID 38825679, 2024). "INS, BGLAP, PTH, IGF1, and TNF were the top 5 most studied genes between osteoporosis and DM." (PMID 35719662, 2022). "His other signs included short stature, osteoporosis, microcephaly and a micropenis with Tanner stage I. Antibodies against insulin and thyroid were negative." (PMID 36061374, 2022). "In osteoporosis subjects, femoral bone mineral density (FBMD) was negatively correlated with age (R = −0.293, P < 0.01), chemerin (R = −0.395, P < 0.01), FBG (R = −0.388, P < 0.01), and insulin (R = −0.388, P < 0.01)." (PMID 26170530, 2015). "In addition, FBMD was negatively correlated with FBG (R = −0.406, P < 0.01) and insulin (R = −0.410, P < 0.01) and LBMD negatively correlated with FBG (R = −0.272, P < 0.01) and insulin (R = −0.315, P < 0.01) in osteoporosis group." (PMID 26170530, 2015). "Additionally, we found out that glimepiride combined with recombinant human insulin injection had a good prognosis for patients; it significantly reduced the bone resorption marker TRACP-5b and prevented the occurrence of complications such as osteoporosis." (PMID 35571731, 2022). "However, small prospective studies have demonstrated that ALN may improve fasting plasma glucose, HbA1c, and insulin indices in prediabetic, osteopenic, postmenopausal women and reduce daily needs for insulin in patients with T1DM and osteoporosis." (PMID 33801212, 2021). "This could explain the osteoporosis commonly observed in hypogonadism and related to a decrease in testosterone independent of insulin activity." (PMID 29844353, 2018). "However, insulin levels were not significantly lower in diabetic patients with osteoporosis, possibly due to a relatively small number of subjects but consistently significant positive correlation was found between insulin and PAI after adjustment for age and BMI." (PMID 26940634, 2016). "However, in a retrospective cross-sectional studyinvolving 856 male T2DM patients, HbA1c and insulin use did not differsignificantly between CVD and non-CVD individuals, and another studyconcluded that age-adjusted HbA1c was not a risk factor for osteoporosis inpostmenopausal women with T2DM." (PMID 39742238, 2024). "In addition, in subjects with osteoporosis, partial correlation analyses suggested a negative correlation of BMD with FBG and insulin." (PMID 26170530, 2015).
preeclampsia (140 papers, 2011 to 2026). Preeclampsia is a hypertensive disorder of pregnancy that is characterized by new-onset hypertension with proteinuria presenting after 20 weeks of gestation, and depending on mild or severe forms may initially present with severe headache, visual disturbances, and hyperreflexia. "The impaired insulin signaling and mitochondrial dysfunction observed in GD can directly impact maternal and fetal health by increasing the risk of complications such as preeclampsia, IUGR, and stillbirth." (PMID 39519193, 2024). "Like preeclampsia, the mechanisms linking GDM and gestational hypertension are not fully understood, but they likely involve shared risk factors such as insulin resistance and inflammation." (PMID 38264369, 2023). "Genome-wide analyses using fetal and parental genotypes identify 40 independent associations influencing placental weight and highlight the role of the fetus in preeclampsia risk and placental growth regulation via insulin signaling." (PMID 37798380, 2023). "Myoinositol reduces the need of insulin treatment and the risk of preeclampsia or gestational hypertension, preterm birth, and neonatal hypogylcemia." (PMID 37836508, 2023). "In logistic regression analysis, the risk was significantly increased in both diet- and insulin-treated groups (vs. background) for large-for-gestational-age newborns, preeclampsia, cesarean section, birth trauma and preterm delivery." (PMID 36014870, 2022). "These benefits include the improvement of insulin sensitivity, decreased systemic inflammation, reduced the risk of preeclampsia, and decreased the incidence of preterm delivery." (PMID 34442765, 2021). "Metformin has been found to reduce the risk of gestational hypertension in comparison to insulin and the risk of preeclampsia when compared to placebo." (PMID 32652973, 2020). "According to the results of another meta-analysis, insulin had significantly higher risk of preeclampsia than metformin." (PMID 33403188, 2020). "Differently, metformin had a lower risk of preeclampsia compared with insulin groups (RR, 0.57; 95% CI, 0.45 to 0.72; P < 0.001)." (PMID 31781670, 2019). "Based on previous research, we hypothesise that higher fasting glucose increases placental weight, likely through fetal insulin mediated growth, and higher placental weight increases the risk of preeclampsia." (PMID 41282652, 2025). "Building on this knowledge, we hypothesise that higher maternal glucose increases fetal insulin secretion, resulting in placental growth that increases the risk of preeclampsia." (PMID 41282652, 2025). "Furthermore, CCL-20 cord blood levels were associated with preeclampsia and fetal leptin, insulin, IL-8, and IL-10 levels, suggesting its role in pregnancy complications, fetal adiposity, and inflammation." (PMID 40698658, 2025). "Furthermore, pregnancy complications like gestational hypertension, premature birth, and preeclampsia are associated with hormonal imbalances, including insulin, cortisol, and thyroid hormones." (PMID 40943494, 2025). "Here, insulin treatment decreased the risk of preeclampsia in ~ 30.0%." (PMID 36419098, 2022). "However, the association with blood pressures tempers this limitation somewhat, and there was sufficient power to detect an association between gestational hypertension and insulin sensitivity." (PMID 28323969, 2017). "Some studies have indicated that the daily consumption of probiotics may reduce the risk of preeclampsia, maintain serum insulin levels and reduce the frequency of GDM in pregnant women." (PMID 27724923, 2016). "In another study, blood glucose and insulin levels were measured 2 hours after a 75 g oral glucose use in pregnant women; results showed that people with high blood insulin levels have higher risk for preeclampsia." (PMID 24812607, 2014).